CASP1 (caspase 1)
Diseases named in the same sentence as CASP1 in open-access papers (continued):
Sharing a sentence is not in itself a finding about the gene and the disease.
infection (continued). "Since then, monocytes and tissue macrophages have emerged as key sentinels of infection and tissue damage via activation of self-assembling pattern recognition receptors (inflammasomes), which trigger inflammation and cell death in a caspase-1 dependent process." (PMID 23226468, 2012). "We could show that only Mtb induced significantly more caspase-1 activation (∼30% positive cells) when compared to uninfected and Mtb esxA mutant infected cells (∼8–12%) at 0h and 4h post infection." (PMID 22911706, 2012). "In addition to ATP-stimulated or Salmonella-infected BMDMs, the p10 fragment, a subunit of active caspase-1, was detected in BMDMs upon infection with live OT." (PMID 22723924, 2012). "However, mature IL-1β was only produced in response to infection with ΔSTY bacteria, which is consistent with our previous finding that ExoS interferes with caspase-1 mediated maturation of IL-1β." (PMID 22844497, 2012). "Caspase-1 activation has been reported to restrict bacterial infection either directly, by affecting bacterial growth, or indirectly, through IL-1β-mediated inhibition of infection." (PMID 22558425, 2012). "Monocytes and tissue macrophages are key sentinels of infection and injury, in large part via activation of self-assembling pattern recognition receptors (inflammasomes) which trigger inflammation and cell death in a caspase-1 and IL-1β dependent process." (PMID 23226468, 2012). "There was a significant 2-fold increase in caspase-1 activation on 3 d post infection." (PMID 22393394, 2012). "In addition, infection of murine macrophages with Y. pestis KIM results in YopJ-dependent activation of caspase-1 and secretion of high levels of IL-1β." (PMID 22563435, 2012). "Thus,macrophages pre-stimulated with LPS are desensitized to undergo YopJ-dependentapoptosis and caspase-1 activation uponYersinia infection." (PMID 21533069, 2011). "We could detect processed caspase-1 at 7.5 h post-infection in TLR2−/− macrophages, but the level was still less than that observed in wild-type macrophages." (PMID 21698237, 2011). "Caspase-1 was required for the processing and release of IL-1β frommacrophages under these infection conditions as shown by infecting wild-type orcasp-1-/- BMDMs with Yp-YopJKIM andisolating IL-1β from infection supernatants by immunoprecipitation." (PMID 21533069, 2011). "In addition, the multiplicityand temporal stage of infection of macrophages with a bacterial pathogen can affectthe requirements for cell death and activation of caspase-1." (PMID 21533069, 2011). "Furthermore, infection of THP-1 cells with vMyxM013-KO virus induced the activation of caspase-1 and processing and secretion of pro-inflammatory cytokines IL-1β and IL-18." (PMID 19851467, 2009). "Whereas, in wild-type macrophages, greater than 60% of the phagosomes containing the pathogen co-localized with LAMP-1 within 30 min post-infection, less than 30% of the L. pneumophila containing vacuoles in caspase-7−/−, caspase-1−/− and A/J-derived macrophages acquired LAMP-1." (PMID 19343209, 2009). "Interestingly, NAIP5 is required to limit the maturation of phagosomes following in vitro infection by L. pneumophila, the agent of Legionnaires disease, and restrict its intracellular replication independently of caspase-1 activation." (PMID 18166077, 2007). "Caspase-1−/− mice, which are inoculated nasally by the agent of bacillary dysentery Shigella flexneri cannot trigger IL-1β–dependent acute inflammation, thereby resulting in exacerbated infection." (PMID 18166077, 2007). "Key pathway inhibitors—including MCC950 (targeting the NLRP3 inflammasome) and VX-765 (a caspase-1 inhibitor)—have shown therapeutic potential in animal models but are limited by suboptimal pharmacokinetics, poor tissue specificity, and risks of immunosuppression and infection during long-term use." (PMID 40832143, 2025).
infection (continued). "Caspase-1 catalyzes the conversion of pro-inflammatory cytokines, such as IL-1β and IL-18, into their biologically active forms, which are then released from the cell to initiate inflammatory responses and recruit immune cells to the location of infection or damage." (PMID 40784044, 2025). "While we predicted that mice lacking both Phox and Caspase 1 would be protected following Mtb infection, we instead observed that these mice were hyper-susceptible to TB, succumbing to disease within 4 weeks of infection." (PMID 40261010, 2025). "Thus, it will be critical to untangle other Aβ functional changes induced by caspase-1 cleavage and whether this relationship defines their switch between salutary or deleterious effects in response to infection." (PMID 38410714, 2024). "Therefore, we assayed cell death and caspase-1 processing in Casp8D387A/D387A BMDMs, which express an uncleavable caspase-8, either after infection with Yptb or treatment with lipopolysaccharide (LPS)/IKK inhibitor (IKKi), which pharmacologically mimics the activity of YopJ." (PMID 39058785, 2024). "Indeed, C. rodentium infection of Casp8–/–Ripk3–/–Casp1–/– mice recapitulated the infection-induced lethality of Casp8–/–Ripk3–/–Casp1/11–/– mice, while both Casp8–/–Ripk3–/–Casp11–/– and Casp8–/–Ripk3–/–Gsdmd–/– mice survived the infection." (PMID 37080966, 2023). "Furthermore, when measuring biomarkers of inflammation during active infection, analyses with area under the curve (AUC) values above 0.75 indicated that caspase-1, ASC, IL-1β and IL-18 are reliable biomarkers of the inflammatory response during active COVID-19 infection." (PMID 37168848, 2023). "Casp1/11/8–/–Ripk3–/– mice, however, should lack the cell death pathways initiated by NLRC4 (via Caspase-1 or Caspase-8), Caspase-11, and TNFα, and our results above suggest that these mice might be highly susceptible to infection." (PMID 36645406, 2023). "Thus, in the early infection period, caspase-1 signaling plays a critical role in viral spread." (PMID 36629424, 2023). "At the same late time of 24 h post-infection, the Ripk3−/− BMDMs showed almost WT levels of activation of many PANoptosis molecules, consistent with the cell death phenotype we observed; however, Ripk3−/− BMDMs continued to show significantly reduced CASP1 and GSDMD activation at the 24 h timepoint." (PMID 38005819, 2023). "In addition, caspase-1 can also mediate the maturation and secretion of the pro-inflammatory cytokines IL-1β and IL-18, resulting in local chronic inflammation, and recruiting more immune cells to the sites of infection thus promoting more cell death." (PMID 36411423, 2022). "In this effort, BMDMs derived from WT, Casp-1−/−, Casp-11−/−, and Casp-1/11−/− mice were infected with R. typhi, R. rickettsii, and R. montanensis, and the levels of IL-1β and IL-1α and cell death, as well as bacterial burdens, were evaluated over the course of infection." (PMID 35130729, 2022). "As our findings indicate that infections with R. typhi and R. rickettsii resulted in a significant reduction of IL-1α secretion, likely via a Casp-11-dependent mechanism, we assessed the expression and activation status of Casp-1 and Casp-11 via Western blot analyses." (PMID 35130729, 2022). "Intriguingly, defective expression of the enzyme NADPH oxidase (Nox2) sensitizes murine neutrophils to Caspase-1-driven neutrophil death upon infection with Pseudomonas aeruginosa, which suggests that under certain conditions neutrophils might be prone to undergo Caspase-1-dependent pyroptosis." (PMID 35849616, 2022). "However, DDX3X deficiency did not restore NLRP3 activation after IAV–ΔNS1 infection, and we instead observed that CASP1 cleavage was reduced in Ddx3xfl/flLysMCre BMDMs compared with Ddx3xfl/fl BMDMs when infected with IAV." (PMID 33766561, 2021).
infection (continued). "Additionally, the S. Typhi ΔtviA and tviA-REP mutant strains induced higher levels of caspase-1, IL-1β, and gasdermin D cleavage as assessed by Western blot compared to the WT S. Typhi strain, indicating greater inflammasome activation upon infection with these mutants." (PMID 33651854, 2021). "Together with long time courses of infection, these factors could contribute to why caspase-1 inhibitors are less efficient than NLRP3 inhibition in preventing primary cell death, which is consistent with previous reports of caspase-independent cell death during Mtb infection." (PMID 32385301, 2020). "Therefore, caspase-1 could influence additional pathology during S. aureus craniotomy infection beyond its role in pro-IL-1β processing; however, this possibility remains speculative." (PMID 32290861, 2020). "Inflammasomes are protein scaffolds required for the activation of caspase-1 and the subsequent release of interleukin (IL)-1β, IL-18, and danger signals, as well as the induction of pyroptotic cell death to restore homeostasis following infection and sterile tissue damage." (PMID 32962268, 2020). "In order to investigate whether the interplay between ROS and the Inflammasome during N. caninum infection was reproducible in vivo, we performed experiments to check the immune responses and parasite burden of WT and Casp-1/11−/− mice, after 3 and 30 days of infection." (PMID 32523898, 2020). "Finally, we also assessed Caspase-1 activity in the lungs of CP-infected mice 1 day post infection." (PMID 31031755, 2019). "However, weight loss (i) did not correlate with viral titers and (ii) was significantly less in caspase-1/11 KO mice compared with WT mice kept at low humidity, indicating that caspase-1/11 KO mice were better able to cope with the same infection and were disease tolerant." (PMID 31085641, 2019). "Pyroptosis was beginning to be noticed in Salmonella and Shigella species infection, starting with the formation of the inflammasomes and leading to the maturation and release of IL-1β and IL-18 and subsequent inflammatory cascade reaction, and was exclusively dependent on caspase-1." (PMID 31814872, 2019). "However, in the presence of LL-37, a 3 hour infection with PAO1 led to an increase in caspase-1 activated NHBE cells (to ~16%) and 16HBE14o- cells, significantly greater than to LL-37 or PAO1 alone, with the same synergistic pattern observed as for IL-1β release." (PMID 30978238, 2019). "Since caspase-1 inhibitor AC-YVAD-CMK also shows inhibitory activity against caspase-4 and caspase-5, which also belong to inflammatory caspases, we asked the question whether caspase-1 plays a prominent role in pyroptosis during the infection of CVB3 and EV71." (PMID 29440739, 2018). "However, CVB3-infection increased the intracellular levels of the cleaved caspase-1 p10 subunit in macrophages (F4/80), NK cells (CD49b) and DCs (CD11c) by 1.7-fold (p < 0.01), 1.9-fold (p < 0.0001) and 1.4-fold (p < 0.01), respectively, in comparison with control mice." (PMID 29434214, 2018). "Moreover, it remains unknown whether the NLRP6 inflammasome is activated by microbial infections and whether NLRP6 co-localizes with ASC and caspase-1 during such infections to induce pyroptosis." (PMID 30248149, 2018). "To analyze the role of caspase-1, caspase-11 and GSDMD in controlling B. abortus infection, we infected knockout (KO) mice for these molecules and we observed that caspase-11 and GSDMD KO animals were more susceptible to infection compared to wild-type animals." (PMID 30589883, 2018). "Taken together, during priming or natural infection with Gram (+ve) or Gram (−ve) pathogenic or commensal bacteria, the UBE2L3 status of host cells sets the upper limit on the amount of pro-IL-1β substrate available for caspase-1 processing and thus controls mature IL-1β production." (PMID 28147281, 2017).
infection (continued). "Prominent among inflammatory pathways in monocytes/macrophages are caspase-1-activating platforms called “inflammasomes” that control maturation and secretion of interleukins such as IL-1β and IL-18, whose potent pro-inflammatory activities direct host response to infection and injury." (PMID 28489580, 2017). "Additionally, infection susceptibility and decreased caspase-1 activity were both fully reversed by injection of non-targetable caiap mRNA, confirming the specificity of the MO." (PMID 29123523, 2017). "In addition, the precise mechanisms of cell death involved during infection remain unclear as at later times post infection, myeloid cell death also appears to involve Asc and Caspase-1/11." (PMID 27926940, 2016). "Therefore, increased lysosomal degradation of L. pneumophila via modulation of the cytoskeleton by caspase-1 might be an attempt to control the intracellular infection before initiation of host cell death." (PMID 27148204, 2016). "In addition, microscopic analysis of infected cells also suggested independent activities of caspase-1 and caspase-11: caspase-1 was found predominantly in single inflammasome ‘specks' following infection whereas caspase-11 was diffusely cytosolic and infrequently (<5%) associated with bacteria." (PMID 27808091, 2016). "The same group showed that mice deficient in both IL-1β /IL-18 are more susceptible than C57BL/6J mice, yet not as much as mice deficient in ASC or caspase-1, suggesting that other caspase-1-dependent pathways, most likely pyroptosis, significantly contributed to protection from infection." (PMID 25768794, 2015). "However, increased expression of UCH-L5, which we observed during infection, could lead to an increased caspase-1 activity in macrophages, which would then promote cell death and release of the bacteria from macrophages." (PMID 26267804, 2015). "Notably, the distribution of F-actin during infection with non-pathogenic E. coli remained unchanged in the presence or absence of caspase-11 and caspase-1." (PMID 26686473, 2015). "Increased IL-1β expression was observed in the LP during acute pathogenic SIV, but not during non-pathogenic infection, suggesting that Caspase-1 activity could be a mediator of lentivirus pathogenesis." (PMID 24495380, 2014). "Interestingly, infections in caspase-1/11 deficient mice showed no defect in bacterial clearance, suggesting that the protective IL-1β response in the lung can arise independently from these inflammasomes." (PMID 25198773, 2014). "A study in seabream leukocytes has revealed that infection of macrophage leads to caspase-1 independent processing and release of IL-1β as well as caspase-1 dependent pyroptotic cell death, suggesting a role for inflammasome and caspase-1 in the clearance of infected immune cells in teleost fish." (PMID 25306446, 2014). "Catalytically active caspase-1 binds to the apoptosis-associated speck-like protein containing a caspase recruitment domain (ASC) subunit of inflammasomes, multiprotein complexes containing pattern recognition receptors (PRRs), which detect infection by pathogens or cellular stress." (PMID 23762029, 2013). "Furthermore, infection with V. parahaemolyticus induced caspase-1 activation (production of p10 fragment by processing procaspase-1 (45 kDa)) and the processing (production of 17 kDa mature form)/release of proIL-1β as well as the release of LDH, a marker of lytic cell death." (PMID 23357873, 2013). "Notably, the difference in the amastigotes numbers of the macrophages derived from the knockouts and the WT mice was not related to the invasion rate of T. cruzi, as similar numbers of amastigotes were observed in the macrophages from WT, NLRP3−/− and caspase-1−/− mice after 2 h of infection." (PMID 24098823, 2013). "However, recent data demonstrated that caspase-1 deficiency does not impair the control of infection by hypercytotoxic Y. pseudotuberculosis (ectopically expressing YopP)." (PMID 24324933, 2013).
infection (continued). "However, whether M. kansasii, a slowly growing NTM, infection could induce caspase-1 activation and IL-1β secretion via the inflammasome activation has not been reported yet." (PMID 22558425, 2012). "After F. novicida escapes the phagosome and replicates in the cytosol of macrophages, it is recognized by the AIM2 inflammasome complex which is essential for controlling F. novicida infection in vivo since mice lacking AIM2, ASC, or caspase-1 are highly susceptible to infection." (PMID 21698237, 2011). "Wild-type, caspase-3−/−, caspase-7−/− and caspase-1−/− macrophages were infected with L. pneumophila and intracellular bacterial replication was evaluated by quantifying the colony forming units (CFUs) throughout 72 hours of infection and by microscopy after 24 hours." (PMID 19343209, 2009). "Our findings revealed that H37Rv infection led to a slight decrease in the N-terminal fragment of GSDMD and cleaved caspase-1, suggesting a subtle inhibition of pyroptosis." (PMID 40738187, 2025). "Cell death within the first 4 h of infection mainly depended on caspase-11, as measured by PI uptake and LDH release, with a modest additional decrease in cell death in Casp1−/−Casp11−/− BMDCs compared to Casp11−/− BMDCs." (PMID 40530878, 2025). "Upregulation of Caspase-1 has been observed in various diseases, including in HIV-infected patients, where Caspase-1 levels are dramatically increased post-infection." (PMID 40944942, 2025). "While ΔespL infection triggered comparable MLKL phosphorylation between WT, Tnfr1−/− and TrifLps2 macrophages, caspase-1 processing, GSDMD cleavage and macrophage lysis were reduced in TrifLps2 macrophages compared to WT and Tnfr1−/− macrophages." (PMID 40128366, 2025). "THP1/PMA macrophages were infected with Lai∆envGFP/G (MOI = 1) in the absence (infection control) or presence of an RT inhibitor (EFV), integrase inhibitor (Ral), and caspase 1/4 inhibitors (zVAD-fmk and VX-765) in the presence of TNFα." (PMID 40920844, 2025). "Compared to mock controls, H6N6 infection significantly upregulated NLRP3, caspase-1, and GSDMD mRNA at 12, and 24 hpi (p < 0.05)." (PMID 41305513, 2025). "The interactions of ASC with molecular components of PANoptosis (e.g., ZBP-1, AIM2, Pyrin, RIPK1, caspase-1, and RIPK3) are observed following infection, and ASC deletion leads to decreased expression of ZBP-1, Pyrin, and caspase-1." (PMID 41304245, 2025). "Compared to the infection group, treatment with levamisole and 25 mg/kg–50 mg/kg of baicalin reduced the NLRP3 and Caspase 1 expression levels (p < 0.05)." (PMID 40427615, 2025). "In contrast, CASP1 and Gasdermin D (GSDMD) expression remains unchanged during the eclipse period of infection but increased significantly at 24 h.p.i." (PMID 40934228, 2025). "Thus, strategies that inhibit caspase-1 activation and gasdermin D-mediated pore formation may reduce the intensity of the inflammatory response without compromising the immune system’s ability to eliminate the infection." (PMID 40333197, 2025). "To evaluate the mechanism through which N. caninum infection regulates IL-1β, we tested MCC950 (an NLRP3 inhibitor), VX765 (a CASP1 inhibitor), and SN-50 (an NF-κB inhibitor) in THP-1 cells following infection with parental strain Nc1 and NcGRA7KO." (PMID 41357231, 2025). "Semi-quantitative analysis showed that caspase-1 and CD163 double-positive signals were significantly increased in the infected group at the early infection when compared with the control group." (PMID 40143222, 2025). "Compared to the infection group, levamisole and 25 to 100 mg/kg of baicalin attenuated NLRP3 and Caspase 1 mRNA expression levels (p < 0.001)." (PMID 40427615, 2025). "To find out how M84 affects AIM2 inflammasome signaling upon infection, we infected J774A.1 macrophages with WT MCMV or the M84stop mutant and analyzed the release of Caspase-1 into the supernatant." (PMID 38278864, 2024).